CTCFL (CCCTC-binding factor like)
Description:
Testis-specific DNA binding protein responsible for insulator function, nuclear architecture and transcriptional control, which probably acts by recruiting epigenetic chromatin modifiers. Plays a key role in gene imprinting in male germline, by participating in the establishment of differential methylation at the IGF2/H19 imprinted control region (ICR). Directly binds the unmethylated H19 ICR and recruits the PRMT7 methyltransferase, leading to methylate histone H4 'Arg-3' to form H4R3sme2. This probably leads to recruit de novo DNA methyltransferases at these sites (By similarity). Seems to act as tumor suppressor. In association with DNMT1 and DNMT3B, involved in activation of BAG1 gene expression by binding to its promoter. Required for dimethylation of H3 lysine 4 (H3K4me2) of MYC and BRCA1 promoters.
Synonyms: CT27; BORIS; dJ579F20.2; CTCF-T; HMGB1L1
Tractability: No criterion of Open Targets' tractability assessment is met for any kind of drug.
Gene: Protein-coding gene on chromosome 20 (57,495,966 to 57,525,652, reverse strand). Ensembl gene ENSG00000124092.
Subcellular location: Cytoplasm; Nucleus
Subcellular location (Human Protein Atlas): Nuclear bodies; Nucleoplasm; Cytosol
Gene Ontology:
Molecular function: DNA binding; DNA-binding transcription activator activity, RNA polymerase II-specific; protein binding; RNA polymerase II cis-regulatory region sequence-specific DNA binding; sequence-specific DNA binding; transcription cis-regulatory region binding; histone binding
Biological process: establishment of protein localization to chromatin; positive regulation of DNA-templated transcription; positive regulation of gene expression; positive regulation of transcription by RNA polymerase II; transcription initiation-coupled chromatin remodeling; genomic imprinting; regulation of transcription by RNA polymerase II; epigenetic regulation of gene expression; regulation of DNA-templated transcription
Cellular component: nucleus; cytoplasm
Genetic constraint (gnomAD): Loss-of-function variants: 36 observed, 71.06 expected, observed/expected ratio (o/e) 0.51, 90% interval 0.39 to 0.67. The upper end of that interval is the gene's LOEUF score, 0.67, which puts it in group 2 of 6, group 1 being the genes least tolerant of losing a copy. Missense variants: 786 observed, 876.29 expected, observed/expected ratio (o/e) 0.9, 90% interval 0.85 to 0.95. Synonymous variants: 324 observed, 320.2 expected, observed/expected ratio (o/e) 1.01, 90% interval 0.92 to 1.11.
Homologues: Orthologues: chimpanzee CTCFL (98% identical), macaque CTCFL (94% identical), dog CTCFL (69% identical), pig CTCFL (68% identical), rat Ctcfl1 (58% identical), mouse Ctcfl (57% identical), zebrafish znf646 (18% identical), zebrafish si:dkey-89b17.4 (16% identical), Drosophila melanogaster mld (11% identical), zebrafish zgc:66472 (10% identical), zebrafish si:ch211-148l7.4 (8% identical). Paralogues in human: CTCF (45% identical), ZNF84 (19% identical), ZNF91 (19% identical), ZNF845 (18% identical), ZNF184 (18% identical), ZNF160 (18% identical), ZNF729 (18% identical), ZNF420 (17% identical), ZNF574 (17% identical), ZNF99 (17% identical), ZNF107 (17% identical), ZBTB48 (17% identical), and 24 more.
Diseases named in the same sentence as CTCFL in open-access papers:
CTCFL is named in the same sentence as 78 diseases in open-access papers, as found by Europe PMC text mining. Sharing a sentence is not in itself a finding about the gene and the disease. The quoted sentences say what the papers report.
breast carcinoma (22 papers, 2008 to 2024). "We previously showed that an immunotherapeutic vaccine targeting the germ cell-specific transcription factor BORIS (CTCFL) was highly effective in treating aggressive breast cancer in the 4T1 mouse model." (PMID 36983050, 2023). "CTCFL can also serve as a promising target of immunotherapy to improve prognosis of breast cancer patients." (PMID 37120564, 2023). "And in breast cancer, CTCFL mediates the tumor occurrence and development in the way of inducing the activation of progesterone and estrogen receptor genes." (PMID 34721660, 2021). "HER2-positive breast cancers with a high CTCFL mRNA expression have a trend towards worse OS compared with counterparts with low CTCFL mRNA expression (HR = 1.67, 95% CI = 0.96–2.89, p = 0.065)." (PMID 30275357, 2018). "In breast cancer, independently of subtypes, survival of patients with high CTCFL mRNA levels is not different from OS of patients with low CTCFL mRNA levels." (PMID 30275357, 2018). "Moreover, recent study indicated that Brother of The Regulator of Imprinted Sites (BORIS, also known as CTCFL), a paralog of CTCF, is aberrantly upregulated in prostate, ovarian, lung and breast cancers and its expression is correlated with tumour characteristics and therapeutic response." (PMID 32941624, 2020). "Conversely, breast cancer displays hypermethylation in the CTCFL promoter and data suggest that CTCFL protein may not be expressed in human breast cancers, although this is controversial." (PMID 30275357, 2018). "It is important to note that even though BORIS (CTCFL) is ranked second, this protein is not present in breast cancer cells." (PMID 38565950, 2024).
ovarian carcinoma (16 papers, 2011 to 2024). A malignant neoplasm originating from the surface ovarian epithelium. "Together, these results provide mechanistic insights into ovarian cancer-associated transcriptional changes while also being potential markers of survival and targets for precision medicine therapies; in particular, in patients with CTCFL overexpression." (PMID 35132075, 2022). "The identified PRAME and CTCFL TCRs are promising candidates for the treatment of patients with ovarian cancer, and are an essential addition to the currently used HLA-A*02:01 restricted PRAME TCRs." (PMID 37026005, 2023). "Our selection of differentially expressed genes, naturally expressed TAA peptides and potent TCRs can improve and broaden the use of T-cell therapies for patients with ovarian cancer or other PRAME or CTCFL expressing cancers." (PMID 37026005, 2023). "CTCFL can induce expression of oncogenes and promote oncogenic properties of carcinomas such as gastric cancer and ovarian cancer." (PMID 37120564, 2023). "Overall, the four TCRs are considered promising candidates for TCR gene transfer strategies in patients suffering from ovarian cancer or other PRAME or CTCFL expressing cancers." (PMID 37026005, 2023). "Next, the CTCFL-specific TCR 39.2E12CTCFL/KLH/A2 was tested for anti-ovarian cancer reactivity and specificity." (PMID 37026005, 2023). "In particular, we found PI3K-Akt initiators; such as the RTKs EGFR1 and VEGFA, and the integrins ITGB3 and ITGB6, to be potential drug targets in ovarian cancer patients with high CTCFL expression." (PMID 35132075, 2022). "BORIS/CTCFL was shown to be upregulated in testicular and ovarian cancer where the encoded protein leads to upregulation of the telomerase reverse transcriptase (hTERT) gene promoting cell immortalization." (PMID 29649096, 2018). "Using the Kaplan Meier plotter the prognostic significance of mRNA levels of CTCFL in gastric, breast, and ovarian cancer were interrogated, similarly to the respective levels of CTCF." (PMID 30275357, 2018). "In stage I and II ovarian cancer patients with a high CTCFL mRNA expression displayed a worse OS compared with counterparts with low CTCF mRNA expression (HR = 2.66, 95% CI = 1.3–5.46, p = 0.0055, not shown)." (PMID 30275357, 2018). "Amerongen72 and colleagues found that the PRAME and CTCFL TCR‐T cells demonstrated potent and specific antitumor reactivity both in vitro and in vivo, the identified PRAME and CTCFL TCRs are promising candidates for the treatment of patients with ovarian cancer." (PMID 38896069, 2024). "According to the TCGA data, CTCFL is mainly expressed in ovarian cancer." (PMID 37026005, 2023). "In ovarian cancer CTCFL expression indeed correlates with advanced stage and decreased survival." (PMID 37026005, 2023). "Taken together, our study elucidates the molecular mechanisms driven by the oncogene CTCFL in ovarian cancer, which may further be utilized as prognostic biomarkers as well as for targeted therapy and drug development." (PMID 35132075, 2022). "Similarly, stage III and IV ovarian cancers suffer worse survival when the CTCFL mRNA level of their tumours is high compared with patients with low levels (HR = 1.26, 95% CI = 1–1.59, p = 0.05)." (PMID 30275357, 2018). "Similarly, the CTCFL TCR‐T cells efficiently recognized ovarian cancer cell lines treated with DAC, implying that pretreatment with DAC may increase the reactivity of transferred TCR‐T cells in patients." (PMID 38896069, 2024). "The dual focus on PRAME and another promising target, CTCFL, reveals the need for precision in the balance of specificity and efficacy in TCR therapies for ovarian cancer." (PMID 39033780, 2024). "In this study, we describe the selection of PRAME, CTCFL and CLDN6 as strictly tumor-specific targets for patients with ovarian cancer." (PMID 37026005, 2023).
ovarian carcinoma (continued). "By performing a differential gene expression analysis using mRNA-seq datasets, PRAME, CTCFL and CLDN6 were selected as strictly tumor-specific TAAs, with high expression in ovarian cancer and at least 20-fold lower expression in all healthy tissues of risk." (PMID 37026005, 2023). "Using panels of primary patient-derived ovarian cancer cells, OVCA cell lines and healthy cell subsets, we ultimately selected three PRAME TCRs and one CTCFL TCR with potent and specific antitumor reactivity in vitro and in vivo." (PMID 37026005, 2023). "The oncogene CTCFL (BORIS), the paralog of CTCF, is a transcriptional factor highly expressed in ovarian cancer (but in rarely any other tissue in females) with cancer-specific characteristics and therapeutic potential." (PMID 35132075, 2022). "We also identified the additional CTCFL targets ACTBL2, MALT1, and PCDH7 to be predictive for ovarian cancer treatment outcomes." (PMID 35132075, 2022). "The selective recognition and destruction of ovarian cancer cells by CTCFL-specific TCRs without impacting healthy cells further exemplify the potential of such targeted therapies." (PMID 39033780, 2024). "By combining mRNA-seq datasets of healthy and tumor tissues, we selected preferentially expressed antigen of melanoma (PRAME), CCCTC-binding factor (CTCFL), and Claudin-6 (CLDN6) as TAAs with high expression in ovarian cancer and at least 20-fold lower expression in all healthy tissues of risk." (PMID 37026005, 2023). "In addition, we consider the three PRAME TCRs (DSK3PRAME/QLL/A2, 16.3C1PRAME/LYV/A24 and 8.10C4PRAME/SPS/B7) and CTCFL TCR (39.2E12CTCFL/KLH/A2) to be promising candidates for the treatment of patients with ovarian cancer, and also for other PRAME or CTCFL expressing cancers." (PMID 37026005, 2023). "In conclusion, CTCFL-specific TCR 39.2E12CTCFL/KLH/A2 demonstrate anti-OVCA reactivity against (DAC-treated) CTCFL positive tumor cells without harming healthy cell subsets and is considered a promising TCR for TCR gene therapy of ovarian cancer." (PMID 37026005, 2023).
melanoma (11 papers, 2009 to 2024). A malignant, usually aggressive tumor composed of atypical, neoplastic melanocytes. "Brother of Regulator of Imprinted Sites (BORIS), also known as CCCTC binding factor-Like (CTCFL), is a transcriptional modulator that becomes aberrantly expressed in melanoma." (PMID 32123577, 2020). "Thus, it appears that CTCFL mutations are often produced by underlying MSI or POLE or POLD1 defects in both cancers commonly associated with these defects (colorectal and endometrial) and in other cancers less commonly associated with them (melanoma)." (PMID 30275357, 2018).
colon carcinoma (7 papers, 2010 to 2020). "Among candidate genes, we focused on CTCFL/BORIS, which has been described as a cancer-testis (CT) antigen, since CTCFL/BORIS was preferentially expressed in side population cells derived from colon cancer cell line SW480." (PMID 26849232, 2016). "In contrast in colon cancer CTCFL amplified samples display a higher CTCFL mRNA expression." (PMID 30275357, 2018).
endometrial carcinoma (5 papers, 2014 to 2018). A malignant tumor arising from the epithelium that lines the cavity of the uterine body. "Another recent and interesting observation is that the DNA methylation status of the testis specific gene CTCFL/BORIS is linked to the level of PR expression in endometrial cancer and premalignant lesions, however causality needs to be explored." (PMID 25415225, 2015). "In the respective endometrial carcinoma TCGA PanCancer Atlas study, which included 509 cases with complete mutations and copy number alterations information, among the 27 cases with CTCFL mutations 22 had mutations in one of the four MSI associated genes or the POLE or POLD1 genes." (PMID 30275357, 2018). "We report for the first time, that CTCF and CTCFL/BORIS seem to diverge in the different subtypes of endometrial cancer; with CTCF mutations occurring in endometrioid subtype and aberrant expression of CTCFL/BORIS being defined to cases of non-endometrioid subtype." (PMID 24658009, 2014). "This suggests CTCFL/BORIS as an Epi-driver gene with a potential for future vaccine development in endometrial cancer." (PMID 24658009, 2014). "We thus propose, CTCFL/BORIS as an Epi-driver gene in endometrial cancer, suggesting a potential for future vaccine development." (PMID 24658009, 2014). "Thus, CTCF and CTCFL/BORIS are found to diverge in the different subtypes of endometrial cancer, with CTCFL/BORIS activation through demethylation from precursors to metastatic lesions." (PMID 24658009, 2014).
ovarian tumor (5 papers, 2014 to 2023). "Finally, the expression level of candidate genes (33 genes + CTCFL) was further analyzed in normal (GTEx) and ovarian tumor (TCGA) samples to assess their prognostic and druggable potential." (PMID 35132075, 2022). "The number of previously identified peptides derived from PRAME, CTCFL and CLDN6 binding in different common HLA class I molecules is limited, as well as solid evidence of processing and presentation in the context of HLA class I on ovarian tumors." (PMID 37026005, 2023).
prostate carcinoma (5 papers, 2011 to 2018). A carcinoma that arises from epithelial cells of the prostate gland. "SPO11 expression is limited to male tissues like CTCFL; the combined expression of these genes in sperm cells is reminiscent of reduced fertility phenotypes associated with CTCFL deficiency in mice and prostate cancer." (PMID 29385718, 2018).
bladder cancer (3 papers, 2010 to 2020). "ChIP assay specificity was controlled by qRT-PCR on GAPDH as a constitutively expressed gene and CTCFL as a developmentally regulated gene weakly expressed in bladder cancer cells." (PMID 33322422, 2020).
cervical cancer (3 papers, 2012 to 2023). A primary or metastatic malignant neoplasm involving the cervix. "In contrast, cervical cancer cell line Ca Ski is positive for CTCFL and this correlates with expression in part of primary cervical carcinoma samples." (PMID 37026005, 2023).
gastric cancer (3 papers, 2018 to 2023). A primary or metastatic malignant neoplasm involving the stomach. "In gastric cancer high CTCFL mRNA expression levels are associated with worse OS compared with gastric cancers having low CTCFL mRNA expression (HR = 1.7, 95% CI = 1.35–2.13, p = 0.000)." (PMID 30275357, 2018). "As DPPA2 is elevated in cancer cells and implicated with cell metastasis in gastric cancer, we reasoned that the TF CTCFL functions on cell malignant behaviors in gastric cancer via targeting DPPA2." (PMID 34721660, 2021). "Collectively, in gastric cancer, TF CTCFL activates DPPA2 to foster cell proliferation, migration, and invasion." (PMID 34721660, 2021). "Meanwhile, our study confirms the targeted relationship between DPPA2 and CTCFL, which may help to develop a novel strategy towards gastric cancer prevention and treatment." (PMID 34721660, 2021). "As we had confirmed that CTCFL could positively mediate DPPA2, to clearly clarify the underlying mechanism in gastric cancer, rescue experiments were further conducted." (PMID 34721660, 2021). "Collectively, CTCFL potentiated cell malignant behaviors in gastric cancer." (PMID 34721660, 2021). "However, the role of CTCFL in gastric cancer, as well as the corresponding regulatory mechanisms, is unexplored." (PMID 34721660, 2021). "In addition, high DPPA2 rescued the repressive impact of CTCFL silencing on the cell proliferation, migration, and invasion in gastric cancer." (PMID 34721660, 2021). "Furthermore, rescue experiments were used to clarify the mechanism of CTCFL/DPPA2 in gastric cancer." (PMID 34721660, 2021). "It was found that CTCFL and DPPA2 were highly expressed in cancer cases, which demonstrated that these two genes might be implicated with the cell characteristics in gastric cancer." (PMID 34721660, 2021). "In sum, this study finds that CTCFL and DPPA2 play an essential part in the malignant progression of gastric cancer, and their expression level may be associated with prognosis." (PMID 34721660, 2021). "We used bioinformatics analysis to know that CTCFL and DPPA2 were both differentially expressed in gastric cancer." (PMID 34721660, 2021). "The transcription factor CTCFL fosters cell proliferative, migratory, and invasive properties via activating DPPA2 in gastric cancer." (PMID 34721660, 2021). "In the current public literatures, CTCFL can mediate the onset and progression of varying cancers, such as liver cancer and neuroblastoma, yet no relevant efforts have been made in gastric cancer." (PMID 34721660, 2021). "CTCFL and DPPA2 were both highly expressed in gastric cancer cells, and high CTCFLL and DPPA2 could promote cell malignant behaviors." (PMID 34721660, 2021). "We described differential CTCFL and DPPA2 expression in gastric cancer tissues." (PMID 34721660, 2021). "In view of these, we could see that overexpressing CTCFL or DPPA2 promotively functions on cell behaviors, but the regulation between themselves or towards gastric cancer is unclear." (PMID 34721660, 2021). "Thus, we could conclude that DPPA2 overexpression suppressed the negative effect of CTCFL silencing on cell malignant phenotypes in gastric cancer." (PMID 34721660, 2021).
lung adenocarcinoma (3 papers, 2017 to 2022). A carcinoma that arises from the lung and is characterized by the presence of malignant glandular epithelial cells. "At present, studies have shown that USP4, EIF2AK3 and CTCFL genes are related to the prognosis of lung adenocarcinoma." (PMID 35785155, 2022).
embryonic cancer (2 papers, 2014 to 2015). "Our findings provide a rationale for investigating therapies that target BORIS/CTCFL in embryonic tumors." (PMID 25279549, 2014).
germ cell tumor (2 papers, 2012 to 2022). A benign or malignant, gonadal or extragonadal neoplasm that originates from germ cells. "In human germ cell tumors, CTCFL is specifically upregulated in spermatocytic seminomas, which are benign testicular tumors originating from a spermatogonium or primary spermatocyte." (PMID 22709888, 2012).
glioma (2 papers, 2018 to 2026). A benign or malignant brain and spinal cord tumor that arises from glial cells (astrocytes, oligodendrocytes, ependymal cells). "Finally, the SNV affecting EE-021 (chr12:3227012C>G) substantially increased the binding affinity of zinc finger protein 57 (ZFP57) and CCCTC-binding factor-like (CTCFL), both related to glioma progression and epigenetic regulation." (PMID 41019514, 2026).
liver cancer (2 papers, 2018 to 2021). An epithelial or non-epithelial malignant neoplasm that arises from the liver. "We found that 6 mRNA expressions were significantly different (P<0.05), including GBP6 (guanylate binding protein), TMEM (transmembrane protein), CTCFL (liver cancer marker gene), KRT5 (keratin 5), LY6D (lymphocyte antigen) and TMEM179 (transmembrane protein)." (PMID 34714841, 2021).